RIPK2 (receptor interacting serine/threonine kinase 2)
Description:
Serine/threonine/tyrosine-protein kinase that plays an essential role in modulation of innate and adaptive immune responses. Acts as a key effector of NOD1 and NOD2 signaling pathways: upon activation by bacterial peptidoglycans, NOD1 and NOD2 oligomerize and recruit RIPK2 via CARD-CARD domains, leading to the formation of RIPK2 filaments. Once recruited, RIPK2 autophosphorylates and undergoes 'Lys-63'-linked polyubiquitination by E3 ubiquitin ligases XIAP, BIRC2 and BIRC3, as well as 'Met-1'-linked (linear) polyubiquitination by the LUBAC complex, becoming a scaffolding protein for downstream effectors. 'Met-1'-linked polyubiquitin chains attached to RIPK2 recruit IKBKG/NEMO, which undergoes 'Lys-63'-linked polyubiquitination in a RIPK2-dependent process. 'Lys-63'-linked polyubiquitin chains attached to RIPK2 serve as docking sites for TAB2 and TAB3 and mediate the recruitment of MAP3K7/TAK1 to IKBKG/NEMO, inducing subsequent activation of IKBKB/IKKB. In turn, NF-kappa-B is released from NF-kappa-B inhibitors and translocates into the nucleus where it activates the transcription of hundreds of genes involved in immune response, growth control, or protection against apoptosis. The protein kinase activity is dispensable for the NOD1 and NOD2 signaling pathways. Contributes to the tyrosine phosphorylation of the guanine exchange factor ARHGEF2 through Src tyrosine kinase leading to NF-kappa-B activation by NOD2. Also involved in adaptive immunity: plays a role during engagement of the T-cell receptor (TCR) in promoting BCL10 phosphorylation and subsequent NF-kappa-B activation. Plays a role in the inactivation of RHOA in response to NGFR signaling.
Synonyms: CARDIAK; RICK; RIP2; CARD3; CCK; GIG30
Tractability: Small molecule: a structure with a bound ligand is known; a high-quality ligand is known; it belongs to a druggable protein family. Antibody: UniProt places it where antibodies can reach, with high confidence; its Gene Ontology location is reachable by antibodies, with high confidence. PROTAC: it is named in the literature on targeted protein degradation; UniProt records ubiquitination sites on it; ubiquitination databases record sites on it; its protein half-life has been measured; a small molecule that binds it is known.
Target class: TKL protein kinase group; Enzyme; Kinase; TKL protein kinase RIPK family; Protein Kinase
Chemical probes: GSK583 (high quality)
Gene: Protein-coding gene on chromosome 8 (89,757,783 to 89,791,064, forward strand). Ensembl gene ENSG00000104312.
Subcellular location: Cytoplasm; Cell membrane; Endoplasmic reticulum
Subcellular location (Human Protein Atlas): Cytosol
Pathways (Reactome):
Immune System: Downstream TCR signaling; Interleukin-1 signaling; JNK (c-Jun kinases) phosphorylation and activation mediated by activated human TAK1; NOD1/2 Signaling Pathway; TAK1-dependent IKK and NF-kappa-B activation; activated TAK1 mediates p38 MAPK activation
Disease: SARS-CoV-2 activates/modulates innate and adaptive immune responses
Metabolism of proteins: Ovarian tumor domain proteases
Signal Transduction: p75NTR recruits signalling complexes
Gene Ontology:
Molecular function: CARD domain binding; caspase binding; identical protein binding; LIM domain binding; protein binding; protein homodimerization activity; protein serine kinase activity; protein tyrosine kinase activity; signaling adaptor activity; signaling receptor binding; JUN kinase kinase kinase activity; protein serine/threonine kinase activity; ATP binding; non-membrane spanning protein tyrosine kinase activity; protein kinase activity
Biological process: apoptotic process; cellular response to muramyl dipeptide; defense response to bacterium; innate immune response; nucleotide-binding oligomerization domain containing 1 signaling pathway; nucleotide-binding oligomerization domain containing 2 signaling pathway; positive regulation of canonical NF-kappaB signal transduction; positive regulation of interleukin-1 beta production; positive regulation of protein K63-linked ubiquitination; positive regulation of protein ubiquitination; protein homooligomerization; toll-like receptor 2 signaling pathway; adaptive immune response; canonical NF-kappaB signal transduction; inflammatory response; positive regulation of interferon-alpha production; positive regulation of interferon-beta production; positive regulation of interleukin-12 production; positive regulation of transcription by RNA polymerase II; signal transduction; T cell receptor signaling pathway; cell surface toll-like receptor signaling pathway; MAPK cascade; positive regulation of apoptotic process; positive regulation of cytokine production; and 3 more
Cellular component: cytoplasm; cytoskeleton; cytosol; endoplasmic reticulum; plasma membrane; protein-containing complex; vesicle
Genetic constraint (gnomAD): Loss-of-function variants: 8 observed, 27.14 expected, observed/expected ratio (o/e) 0.29, 90% interval 0.17 to 0.53. The upper end of that interval is the gene's LOEUF score, 0.53, which puts it in group 2 of 6, group 1 being the genes least tolerant of losing a copy. Missense variants: 259 observed, 336.35 expected, observed/expected ratio (o/e) 0.77, 90% interval 0.69 to 0.85. Synonymous variants: 118 observed, 122.97 expected, observed/expected ratio (o/e) 0.96, 90% interval 0.83 to 1.12.
Homologues: Orthologues: chimpanzee RIPK2 (99% identical), macaque RIPK2 (97% identical), rabbit RIPK2 (90% identical), pig RIPK2 (88% identical), dog RIPK2 (86% identical), rat Ripk2 (85% identical), mouse Ripk2 (84% identical), guinea pig RIPK2 (67% identical), tropical clawed frog ripk2 (52% identical), zebrafish ripk2 (39% identical). Paralogues in human: MAP3K9 (19% identical), MAP3K10 (19% identical), MAP3K21 (19% identical), MAP3K11 (18% identical), LRRK2 (18% identical), TESK2 (18% identical), MAP3K12 (17% identical), MAP3K13 (17% identical), MAP3K20 (17% identical), RIPK1 (17% identical), RIPK3 (17% identical), TESK1 (17% identical), and 11 more.
Diseases named in the same sentence as RIPK2 in open-access papers:
RIPK2 is named in the same sentence as 141 diseases in open-access papers, as found by Europe PMC text mining. Sharing a sentence is not in itself a finding about the gene and the disease. The quoted sentences say what the papers report.
colitis (21 papers, 2013 to 2026). Inflammation of the colon. "Consistent with the protective role of NOD2 signaling in colitis, deficiency of RIPK2 significantly exacerbated colitis in Yod1+/+ mice." (PMID 39333628, 2024). "Taken together, the data show that RIPK2 inhibition can ameliorate the gut inflammation and pathology associated with Irgm1 deprivation in mouse colitis models." (PMID 36221902, 2022). "Mice deficient in NOD2 or RIPK2 are more susceptible to DSS or TNBS-induced colitis; however, the administration of RIPK2 inhibitors ameliorates chronic colonic inflammation." (PMID 33935757, 2021). "In mice, a deficiency in RIPK2 can cause dysbiosis, which is a microbial imbalance in the colon, which in turn predisposes mice to communicable colitis and colitis-associated CRC." (PMID 34356990, 2021). "Wild-type mice that received disease-predisposing bacterial communities from NOD2 or RIPK2-deficient mice via co-housing or cross-fostering experiments suffered from increased susceptibility to DSS-induced colitis and colitis-associated carcinogenesis." (PMID 24409180, 2013). "Finally, the administration of RIPK2 siRNA protected NOD1- or NOD2-deficient mice from DSS-induced colitis, suggesting that RIPK2, activated by TLR2 and/or TLR4, plays a colitogenic role." (PMID 39403381, 2024). "Moreover, mice deficient in NOD2 or RIPK2 displayed enhanced susceptibility to DSS-induced colitis due to intestinal dysbiosis." (PMID 33935757, 2021). "Aberrant activation of RIPK2 is closely associated with increased expression of signaling molecules in the colonic mucosa of IBD patients, and blocking RIPK2 activation effectively inhibits the development of experimental colitis in mice." (PMID 41495287, 2026). "In the present study, we found that NOD2-mediated protective responses in colitis were potentiated by YOD1, which inhibited the proteasomal degradation of RIPK2 by removing K48-linked polyubiquitin chains." (PMID 39333628, 2024). "To directly confirm that YOD1 regulates colitis through RIPK2, we silenced RIPK2 in Yod1+/+ and Yod1−/− mice with adeno-associated virus (AAV)." (PMID 39333628, 2024). "The deubiquitinating enzyme YOD1 potentiates protective NOD2 signaling by stabilizing RIPK2, thereby ameliorating intestinal inflammation and colitis." (PMID 39333628, 2024). "Next, we explored the therapeutic potential of targeting both RIPK2 and TRAF6 in colitis and colitis-associated CRC." (PMID 33893298, 2021). "RIPK2 is associated with the NFKB pathway and seems to have a role in colitis-associated CRC, where the level of expression of RIPK2 was significantly higher in the colonic mucosa of patients with ulcerative colitis compared to controls." (PMID 34356990, 2021). "This idea is fully supported by our recent report in which NOD1 or NOD2-independent activation of RIPK2 mediates experimental colitis." (PMID 33935757, 2021). "These molecules are therefore potentially interesting tools with which to further explore RIPK2 function in pre-clinical models of colitis and other inflammatory conditions." (PMID 26320862, 2015). "In line with published findings that NOD2−/− and RIPK2−/− mice are more susceptible to DSS-induced colitis than control mice, we found that Yod1−/− mice, accompanied with reduced RIPK2 levels, also developed more severe experimental colitis than did control mice." (PMID 39333628, 2024). "In 2004, an early study showed that the p38 mitogen-activated protein kinase (MAPK) inhibitor SB203580 could suppress DSS-induced experimental colitis via inhibiting NOD2 effector RIPK2 in the NOD2/RIPK2/NF-κB signaling pathway." (PMID 37833958, 2023). "Since we found that IRGM negatively regulates RIPK2‐dependent pro‐inflammatory responses, we hypothesized that therapeutic inhibition of RIPK2 could reduce gut inflammation associated with Irgm1 depletion in shigellosis‐ and DSS‐induced colitis models." (PMID 36221902, 2022).
colitis (continued). "Furthermore, the blockage of RIPK2 activation ameliorates the development of experimental murine colitis." (PMID 33935757, 2021). "Therefore, it is likely that RIPK2 inhibitors prevent experimental colitis through the suppression of polyubiquitination of RIPK2." (PMID 33935757, 2021). "Several RIPK2 inhibitors have been used for the treatment of experimental colitis." (PMID 33935757, 2021). "We speculate that the NOD2-RIPK2 and TLRs-RIPK2 pathways play anti-inflammatory and pro-inflammatory roles, respectively, in the development of experimental colitis." (PMID 33935757, 2021). "Activation of RIPK2 plays dual roles in the development of experimental colitis." (PMID 33935757, 2021). "Protection by the intact NOD2–RIPK2 pathway against experimental IBD required polyubiquitination of RIPK2 as MDP activation of NOD2 did not ameliorate DSS-induced colitis in mice deficient in cIAP2 or Pollino3, the E3 ligases for K63-linked polyubiquitination of RIPK2." (PMID 33935757, 2021). "Treatment of Irgm1−/− mice with the RIPK2 inhibitor GSK583 significantly ameliorated the acute colitis symptoms (and EV5A and B)." (PMID 36221902, 2022). "We found that the combination of both RIPK2 and TRAF6 inhibitors appeared to synergistically ameliorate colitis." (PMID 33893298, 2021). "Moreover, Yod1+/+ and Yod1−/− mice had similar disease severity after RIPK2 knockdown, indicating that YOD1 affects colitis by regulating RIPK2." (PMID 39333628, 2024). "Interestingly, the RIPK2-specific siRNA also diminished TNBS induced colitis in both NOD2-deficient and NOD1/NO2-double deficient mice, indicating the effect of RIPK2 on colitis was independent of either NOD1 or NOD2 signaling." (PMID 36959850, 2023). "The inhibition of DSS-induced colitis by NOD2 activation required a molecular interaction between NOD2 and RIPK2, because administration of MDP failed to prevent colonic inflammation in mice deficient in RIPK2." (PMID 33935757, 2021).
breast carcinoma (13 papers, 2013 to 2025). "RIP2 expression correlated with the tumor size, metastasis, overall staging, progression-free survival, and body mass index (BMI) of patients with breast cancer, and RIPK2 polymorphism was also involved in the development of bladder cancer." (PMID 34356990, 2021). "The association we found between RIPK2 activity and advanced tumor size, metastasis status, cancer stage and BMI suggest that RIPK2 could be a prognostic marker for breast cancer and IBC progression." (PMID 29874851, 2018). "In breast cancer, RIPK2 was shown to promote breast cancer cell migration and invasion upstream of NFκB signaling." (PMID 31404997, 2019). "In fact, quantitative mass spectrometry-based proteomic and phosphoproteomic analyses of 105 breast cancer data have reported that RIPK2 has a similar gene amplification pattern to HER2 and that HER2 amplification showed an increase level of phosphoproteins." (PMID 29874851, 2018). "This is the first study that addresses RIPK2 activity increase in IBC compared to other types of breast cancer." (PMID 29874851, 2018). "The correlation of RIPK2 activity with advanced tumor size, metastasis status, cancer grouping stage and possibly BMI suggests that RIPK2 could be a marker for all breast cancer and specifically IBC progression." (PMID 29874851, 2018). "Although RIPK2 has been extensively studied in other types of cancers especially colorectal cancer because of its link to NOD2 mutation, little is known about the NOD2-RIPK2 pathway in breast cancer." (PMID 29874851, 2018). "Hence, these results not only highlight that RIPK2 is a novel prognostic biomarker in breast cancer, but also suggest that targeting RIPK2 may improve the outcome of advanced breast cancer patients with RIPK2 amplification or overexpression." (PMID 37324457, 2023). "Erbin, which interacts with Erbb2, is downregulated in HER2-overexpressing breast cancer cells and it can form a complex with NOD2 to inhibit RIPK2 activity." (PMID 40406369, 2025). "Erbin was found to be downregulated in Her2-overexpressing breast cancer cells, can form a complex with NOD2 (the obligate receptor for RIPK2) and work as a negative regulator of its activity." (PMID 29874851, 2018). "Indeed, we can demonstrate that RIPK2 activity correlated with advanced tumor, metastasis, and group stage as well as body mass index (BMI) to indicate that RIPK2 might be a useful prognostic marker for IBC and advanced stage breast cancer." (PMID 29874851, 2018). "Previous studies have shown that RIPK2 promotes the development of metastatic tumor tissues 6 and inflammatory breast cancer (IBC) 43, while the suppression of RIPK2 can hinder the migration of BC cells and reduce the occurrence of extrapulmonary metastasis." (PMID 38164277, 2024).
Crohn disease (12 papers, 2015 to 2025). A gastrointestinal disorder characterized by chronic inflammation involving all layers of the intestinal wall, noncaseating granulomas affecting the intestinal wall and regional lymph nodes, and transmural fibrosis. "Defects in NOD/RIPK2 signaling are associated with numerous inflammatory diseases, including asthma, sarcoidosis, inflammatory bowel disease (Crohn’s disease and ulcerative colitis), multiple sclerosis, and Blau syndrome." (PMID 36959850, 2023). "Dysregulation of NOD/RIPK2 signaling is implicated in the development of several inflammatory diseases, including sarcoidosis, Blau syndrome, Crohn’s disease (CD), and ulcerative colitis (UC)." (PMID 36959850, 2023). "Using an overexpression system, we analyzed ~50 NOD2 polymorphisms reportedly connected to Crohn’s disease to determine if they also displayed loss of function and if this could be related to alterations in protein localization and/or association with RIPK2." (PMID 26500656, 2015). "Mutations in ATG16L1, linked to Crohn’s disease, interfere with the interaction between NOD2 and RIPK2, resulting in the suppression of RIPK2 signaling and heightened inflammatory responses." (PMID 40406369, 2025). "Previous studies have indicated that RIPK2 is related to innate immunity, inflammation, and autophagy and is involved in atherosclerosis, bacterial or viral infection, Crohn's disease, and so on." (PMID 31485193, 2019). "Further proof of concept was subsequently attained using the clinical epidermal growth factor receptor inhibitor, gefitinib, which also inhibited RIPK2 and improved disease burden in a spontaneous model of Crohn's disease-like ileitis." (PMID 26320862, 2015). "This approach was first validated using SB203580, a pyridinyl imidazole inhibitor of p38, which showed additional inhibition of RIPK2 in vitro and was efficacious in a Crohn's disease model in mice." (PMID 26320862, 2015). "In contrast, mutations in the second major Crohn's disease susceptibility factor, ATG16L1, disrupt an inhibitory interaction with NOD2 and consequently increase the activation of RIPK2." (PMID 26320862, 2015). "Furthermore, patients with Crohn’s disease or ulcerative colitis exhibited elevated RIPK2 expression, while NOD2 expression remained unchanged in these conditions." (PMID 40406369, 2025). "In this work, we have analyzed 53 Crohn’s disease-associated SNPs for their effect on three key functional consequences of NOD2 stimulation, namely: basal and ligand-induced NFκB-driven signaling, interaction with RIPK2, and membrane localization." (PMID 26500656, 2015). "Excessive RIPK2 activation has also been reported in pediatric Crohn's disease." (PMID 26320862, 2015). "Indeed, RIPK2 is an attractive drug target for many inflammatory conditions, particularly for inflammatory conditions of the gut, such as Crohn’s disease and inflammatory bowel disease, as well as early onset sarcoidosis, Blau syndrome, inflammatory breast cancer, and multiple sclerosis." (PMID 37777791, 2023). "RIPK2 is a therapeutic target for autoimmune and inflammatory diseases such as inflammatory bowel disease (IBD) and Crohn’s disease and is an emerging therapeutic target in metastatic castration-resistant prostate cancer." (PMID 40737275, 2025). "RIPK2 inhibitors have shown benefit in inflammatory disease including in the SAMP1/YitFc model of Crohn’s disease-like ileitis although there are no clinical studies as yet in intestinal inflammation." (PMID 29515999, 2018).